PLAC4 (placenta associated 4)
Synonyms: MGC126664; MGC126666; PRED78; formerly C21orf115
Gene: Long non-coding RNA gene on chromosome 21 (41,171,944 to 41,186,807, reverse strand). Ensembl gene ENSG00000280109.
Diseases named in the same sentence as PLAC4 in open-access papers:
PLAC4 is named in the same sentence as 6 diseases in open-access papers, as found by Europe PMC text mining. Sharing a sentence is not in itself a finding about the gene and the disease. The quoted sentences say what the papers report.
colorectal cancer (1 paper, 2025). A primary or metastatic malignant neoplasm that affects the colon or rectum. "This resulted in the identification of 17 significantly mutated genes, including 16 of which have been described previously as significantly mutated in colorectal cancer and PLAC4, which has not previously been described." (PMID 41413856, 2025).
congenital heart disease (1 paper, 2021). A heart disease that is present at birth. "PLAC4 is associated with congenital heart disease and hypertrophic cardiomyopathy." (PMID 34336943, 2021).
PLAC4 also shares sentences with these, for which no sentence is quoted: asthma (1 paper); cancer (1); hypertrophic cardiomyopathy (1); tumor (1).